KIT (KIT proto-oncogene, receptor tyrosine kinase)
Diseases named in the same sentence as KIT in open-access papers (continued):
Sharing a sentence is not in itself a finding about the gene and the disease.
melanoma (continued). "This anatomic distribution further supports the hypothesis that KIT-driven melanomas are biologically and clinically distinct from other melanoma subtypes that are primarily driven by more common alterations involving the MAPK pathway." (PMID 41301010, 2025). "The combination of KIT inhibitors with immune checkpoint inhibitors is a potential therapeutic avenue that warrants further exploration, given the promising synergistic effects observed in other melanoma subtypes." (PMID 40003600, 2025). "Patient characteristics also contribute to the clinico-genetic profile of KIT-mutant melanoma." (PMID 41301010, 2025). "Patients must be selected for activating KIT mutations to derive benefit, as studies in populations with unselected or amplification-only melanoma have shown limited to no TKI efficacy." (PMID 41301010, 2025). "One study also reported that KIT-mutant melanomas tend to exhibit more aggressive histopathologic features, such as ulceration, vascular invasion, and increased Breslow thickness, which may contribute to or reflect intrinsic resistance phenotypes." (PMID 41301010, 2025). "These mutations are linked to shorter OS compared to patients without KIT alterations, indicating that KIT mutations serve as an adverse prognostic factor in melanoma." (PMID 40867277, 2025). "Notably, as melanoma progresses, the expression of the receptor tyrosine kinase c-KIT decreases, while levels of miR-221/222 increase, indicating a negative correlation between miR-221/222 and c-KIT expression." (PMID 41515546, 2025). "These KIT mutations are consistently found in acral melanomas but absent in nevi from the same sites, suggesting a distinct oncogenic pathway." (PMID 41301010, 2025). "Population-level studies estimate that approximately 11–23% of acral melanomas, 15–21% of mucosal melanomas, and up to 27% of CSD melanomas harbor KIT mutations, whereas the prevalence in non-CSD cutaneous melanoma is generally less than 5%." (PMID 41301010, 2025). "The only patient with a KIT mutation developed delayed-onset brain metastases, while no patients with quadruple negative melanoma (lacking mutations in BRAF, NRAS, NF1, or KIT) developed CNS involvement." (PMID 41301010, 2025). "Similarly, new KIT inhibitors with improved potency and selectivity are under evaluation for KIT-mutant melanoma, a rare but challenging subtype with limited treatment options." (PMID 41302945, 2025). "Three out of four patients who achieved PR in stage II had melanomas of the KIT+ acral subtype." (PMID 39858514, 2025). "In contrast, high-CSD melanomas frequently lack BRAF V600E mutations but may have alterations in genes such as NRAS, NF1, and KIT while exhibiting a higher TMB." (PMID 40125165, 2025). "One study investigated the relationship between pre-treatment and the early on-treatment detection of BRAF, NRAS and KIT alterations in ctDNA using ddPCR and treatment outcome in 76 melanoma patients treated with nivolumab alone or in combination with ipilimumab." (PMID 39859576, 2025). "Finally, the experiments of c-KIT alteration, including c-KIT knockout and overexpression, confirmed its critical role in Artemisinin's effect on melanoma." (PMID 39744440, 2025). "Therapies targeting c-KIT mutations, although not yet formally approved, have shown promising results in treating melanomas harboring these genetic alterations." (PMID 38474231, 2024). "In some patients, we could also exclusively detect mutations in melanoma driver genes (BRAF, NRAS, MAP2K1, KIT) suggesting that CTC analysis could complement ctDNA analysis for relevant clinical implications in personalized medicine in oncology." (PMID 38898234, 2024). "While KIT mutations in canine melanoma are not as common as in other cancers like canine mast cell tumors, their identification can critically inform treatment decisions and highlight potential therapeutic targets." (PMID 39408717, 2024).
melanoma (continued). "More importantly, BRAF V600E mutations comprised 93% of all BRAF mutations in that study cohort, and no c-KIT mutations were identified, which is more characteristic of melanoma arising from acral skin and mucosal sites." (PMID 39473498, 2024). "For instance, canine melanoma with specific genetic mutations, such as NRAS and KIT, may be particularly amenable to treatment with small molecule inhibitors that target these mutations." (PMID 39408717, 2024). "Key genetic drivers central to melanoma development, such as mutations in the BRAF, NRAS, and c-KIT genes, are discussed alongside the latest WHO classification, which categorizes melanomas based on cumulative sun damage (CSD), which correlates with specific molecular alterations." (PMID 38474231, 2024). "However, despite the lower frequencies, BRAF, NRAS, KRAS, and KIT are somatic SNVs identified in canine melanomas, accounting for 1.8% (5/272), 8.0% (25/311), 13.1% (27/206), and 22.9% (16/70), respectively." (PMID 38397192, 2024). "High‐CSD melanoma frequently harbors NRAS, BRAF non‐V600E, and KIT mutations." (PMID 39564955, 2024). "Mucosal (MM) and acral melanomas (AM) are rare melanoma subtypes of unmet clinical need; 15%–20% harbor KIT mutations potentially targeted by small-molecule inhibitors, but none yet approved in melanoma." (PMID 38417447, 2024). "Throughout this review, we have explored the genetic landscape of melanoma, highlighting the importance of mutations in key genes such as BRAF, NRAS, and KIT, as well as the relevance of epigenetic modifications and interactions with the tumor microenvironment." (PMID 39200315, 2024). "Out of 462 melanoma samples, 322 (69.7%) were positive for Tier I/II variant and 8 patients had variants in two genes (5 patients with BRAF and NRAS; 3 patients with BRAF and KIT)." (PMID 37483495, 2023). "For the primary melanoma cell line—WM3211 (VGP), with a wild type for BRAF, PTEN, N-RAS, and CDK4, and with a mutation at position 576 in the c-KIT gene, caspase 3 activation compared to the control was several times lower than for the metastatic lines Mel-1359 and MEWO." (PMID 37097377, 2023). "It has been shown that Imatinib may be effective in patients with melanoma harboring c-KIT alterations." (PMID 37372988, 2023). "In addition to BRAF, other genes have been found mutated in sporadic melanomas including NRAS, TERT, NF1, and KIT." (PMID 37627054, 2023). "However, when the three major drivers, BRAF, RAS and KIT, are wild type, the remaining tumors, called here triple-wild-type melanomas (TWMs), are genetically very heterogenous and very different from the rare histological ones." (PMID 36980598, 2023). "One study comparing NAM (n = 54) and non-NAM acral melanoma (n = 78) revealed that, among common melanoma driver genes, mutations in KIT and KRAS were predominantly found in NAM, whereas those in BRAF and NRAS occurred almost exclusively in acral melanoma." (PMID 36983205, 2023). "Mutational profile of mucosal melanomas is known to differ from their cutaneous counterparts, suggesting a different pathway in the pathogenesis: They harbor lower BRAF and TERT, and relatively higher NRAS and KIT mutation frequencies." (PMID 35642348, 2023). "The differential expression rule of gene KIT extracted by EDST might be the key factor in the study of the A375 melanoma cell line." (PMID 37644423, 2023).
melanoma (continued). "In a study, 130 KIT-altered melanoma patients were pooled from five medical centers." (PMID 36588679, 2022). "High c-KIT expression is observed in 64 to 88% of melanomas." (PMID 35159045, 2022). "The MassARRAY-based OncoFOCUS panel (v3) was previously adopted in our community pathology lab as a fully validated clinical test of common mutations in BRAF, EGFR, KIT, KRAS, and NRAS genes, which are implicated in various cancers, particularly colon cancer, lung cancer and melanoma." (PMID 35446881, 2022). "Clinical guidelines strongly recommend testing BRAF, NRAS and KIT in all melanomas." (PMID 35159047, 2022). "In addition to GISTs, KIT inhibitors have also been tried in other tumor types with KIT alterations, particularly in KIT‐altered melanoma." (PMID 36254250, 2022). "KIT mutations are typically found in melanomas on mucosal and acral areas, which points toward non-UV exposures." (PMID 35712493, 2022). "Although KIT activating mutations have been found to drive transformation in GIST, acute myeloid leukemia, mast cell leukemia, and melanoma, no gain-of-function mutations on KIT have been reported in neuroblastoma." (PMID 34716856, 2022). "IHC profiling of different melanoma subtypes showed the importance of alterations in the KIT gene, this genetic data may constitute a therapeutic target." (PMID 35371814, 2022). "In the context of melanoma, prevalent mutations in BRAF, NRAS, MEK, and KIT oncogenes have already made possible the development of specific targeted therapies directed at the MAPK/ERK pathway, often constitutionally activated in melanoma." (PMID 36143375, 2022). "In addition, the most frequent and well-known genetic alterations occurring in melanoma are linked to the BRAF, NRAS, KIT, and NF1 genes." (PMID 36431075, 2022). "Nilotinib was also deemed safe and effective for KIT-mutant rare melanomas." (PMID 35513054, 2022). "Non-CSD melanomas develop typically in younger patients and predominantly carry BRAF mutations, while CSD melanomas have a higher mutation burden, more often contain NF1, NRAS or KIT mutations and affect older people at the distal extremities and head and neck region." (PMID 35328746, 2022). "For patient 2, a point mutation c.1936T>G in c-KIT exon 13 produces the missense amino acid alteration p.Y646D, which was not reported in GISTs or melanoma previously." (PMID 35720122, 2022). "However, in erythroleukemic cells, EPO downregulates KIT expression and malignant transformation of melanocytes leads to a loss of KIT expression and upregulation of EPOR expression in melanoma cells." (PMID 35887076, 2022). "Melanoma driven by V600K mutations is thought to have unique features compared to V600E, including decreased reliance on MAPK/ERK pathway over activation, increased expression of c-KIT, and upregulation of the PIK3CB-AKT anti-apoptotic pathway." (PMID 35954441, 2022). "c-KIT is a component of RTKs (class III transmembrane receptor tyrosine kinases) and its mutations are rare (less than 3%), being related to acral, mucosal, or chronically sun-exposure melanomas." (PMID 35334544, 2022). "An active phase I/II study to determine pexidartinib safety, pharmacokinetics, and preliminary efficacy in unresectable or metastatic KIT-mutated melanoma was launched in 2015 but is not recruiting anymore." (PMID 33918490, 2021). "In a word, compared with gynecologic melanoma, non-gynecologic melanoma harbored distinct mutation rates in KIT, BRAF, SF3B1, KRAS and NRAS genes." (PMID 34102999, 2021). "Indeed, melanoma cells express c-KIT, PDGF-R, and Abl, and an autocrine growth loop mechanism has been described for the receptor–ligand interaction of PDGF-R/PDGF, as well as for c-KIT/SCF." (PMID 33918490, 2021). "A previous study has indicated that KIT signaling is critical for the proliferation and migration of melanoma cells, raising the possibility that this might be a promising therapeutic target in patients with aggressive oral melanoma." (PMID 35048028, 2021).
melanoma (continued). "KIT mutations were significantly more frequent in acral (3/36; 8.3%) and mucosal (4/8; 50%) melanomas than in non-acral cutaneous melanomas." (PMID 33648909, 2021). "Despite that, a second generation of KIT inhibitors were developed and expected to be more efficient; as they bind to both active and inactive conformations of c-KIT, imatinib remains the c-KIT inhibitor of choice in comparison to other c-KIT inhibitors in melanoma." (PMID 33918490, 2021). "5-year estimated melanoma-specific and overall survival of patients with KIT mutated melanomas was 77.6% and 73.3%, whereas those without mutations was 82% and 87.5%." (PMID 33648909, 2021). "Some case reports suggested the efficacy of other TKIs in melanomas with KIT alterations." (PMID 34831002, 2021). "However, about 70% of c-KIT mutations occur in exon 11, with preponderance of L576P that shows poor sensitivity to imatinib in GIST, but variable sensitivities in melanoma." (PMID 33918490, 2021). "In a large series of 706 mucosal melanomas, KIT and BRAF mutational status did not correlate with overall survival (OS); however, NRAS was not analyzed in this series." (PMID 34571863, 2021). "Given the revolution that targeted drugs constituted as inhibitor-based drugs against melanomas harbouring mutations in BRAF, MEK, and KIT, studies like the present one contribute to the identification of potential lines of work aimed at improving the medical attention of these patients." (PMID 34680367, 2021). "In addition, genes encoding protein tyrosine kinases, KIT and EPHA5, relevant receptors upstream of the MAPK pathway, are particularly highly expressed in the melanoma compared to BAP1-inactivated nevus." (PMID 35052351, 2021). "Gene expressions in mucosal melanomas like c‐KIT, NRAS or BRAF might be of potential use for selective inhibitors." (PMID 33844113, 2021). "The frequency of KIT mutation in our series was much higher than rates reported in studies on non-gynecologic melanoma." (PMID 34102999, 2021). "Among c-KIT inhibitors, imatinib appears to display both efficacy and safety in melanoma." (PMID 33918490, 2021). "Polymerase Chain Reaction (PCR) and Sanger sequencing techniques were performed to identify the mutational status of BRAF, NRAS, KRAS, NF1, KIT, PDGFRA and SF3B1 on 19 melanomas of the female genital tract, paired with 25 cutaneous melanomas, 18 acral melanomas and 11 melanomas of nasal cavity." (PMID 34102999, 2021). "KIT (C-KIT/CD117) gene mutations show heterogeneous distribution through the gene and they have been detected in hot-spots at exon 9 (c459/465/471/483), 11 (c551/559/576), 13 (c642), and 17 (c816), accounting for 5-15% of mutations of diagnosed melanomas." (PMID 34123788, 2021). "In accordance, a phase 2 clinical trial of nilotinib in Korea for KIT mutant/amplified melanoma patients (UN10-06) indicates the safety and efficacy of nilotinib without showing any outperformance over imatinib effect in terms of progression free and overall survival." (PMID 33918490, 2021). "In addition, mutations in KIT (the receptor for stem cell factor, SCF) have been found in ~15% of mucosal melanomas." (PMID 35048028, 2021). "However, responses to tyrosine kinase inhibitors (imatinib, sorafenib) have been reported in patients with KIT-mutant melanoma." (PMID 34441278, 2021).
melanoma (continued). "In summary, KIT is evolving as an important therapeutic target in advanced melanomas." (PMID 34831002, 2021). "In an open-label, non-controlled study, unresectable melanoma patients with a proven c-KIT mutation were evaluated for Imatinib response, demonstrating notable radiographic improvement." (PMID 34064058, 2021). "In our cohort, survival was worse in KIT-mutated melanomas but differences were not statistically significant, most likely due to the small number of KIT-mutated cases." (PMID 33648909, 2021). "However, disease control rates varied depending on the KIT status, with patients with KIT-mutant melanoma gaining a higher benefit than those with KIT amplification." (PMID 34149718, 2021). "There is also preclinical evidence that ponatinib may have a role in the treatment of KIT mutant melanomas." (PMID 34831002, 2021). "In addition to NRAS mutations, several receptor tyrosine kinases (RTKs) such as c-KIT, EGFR, MET, and VEGFR have been reported to be involved in melanoma progression, invasion, or resistance to therapies, mainly targeting the MAPK pathway." (PMID 33918490, 2021). "However, it has recently been reported that two canine melanoma cases achieved an objective response after treatment with another kinase inhibitor, masitinib, which targets KIT." (PMID 33827546, 2021). "Preliminary clinical results, showed a promising and durable response, with nilotinib in c-KIT metastatic melanoma patients showing mutation in exon 11, but nilotinib anti-tumor activity in melanoma patients with KIT amplification was not clear at this time." (PMID 33918490, 2021). "None of the nevus-associated melanomas had KIT mutation, and none of the melanomas harboring BRAF mutation carried a KIT mutation." (PMID 33648909, 2021). "Moreover, nilotinib, a KIT-selective tyrosine kinase inhibitor, was evaluated in the phase II TEAM trial in patients with KIT-mutated advanced melanoma, resulting in similar activity to historical data from imatinib-treated patients." (PMID 33964953, 2021). "This mutation is previously not reported in GIST but in a patient diagnosed with melanoma, who also displayed a KIT W557R mutation." (PMID 34552011, 2021). "Mutations in c-KIT have been found in up to 28% of melanomas on chronically sun-damaged skin, but not in non-acral melanomas, unrelated to chronically sun-damaged skin." (PMID 33807778, 2021). "It should be noted that melanoma, angiosarcoma, Ewing’s sarcoma, childhood neuroblastoma, seminoma, and small cell lung carcinoma may also show expression of the KIT protein by IHC." (PMID 34202544, 2021). "Likewise, copy number variations (CNV) have been identified in certain genes in association with melanomas, such as in PTEN, CDKN2A, and KIT." (PMID 34831002, 2021). "Interestingly, while KIT expression is initially upregulated in early melanoma, it is often markedly downregulated in later stage disease." (PMID 35008286, 2021). "Novel therapeutic approaches targeting genetic mutations in BRAF, MEK, RAS family of proteins, c-KIT, c-Met, VEGFR, and PI3K have been illustrated and implicated in the reduction of cell proliferation and cell survival in melanoma as well other forms of cancer." (PMID 33807778, 2021). "Patients with KIT-mutant melanoma showed limited response rate to KIT inhibitors and ICI." (PMID 33918490, 2021). "Patients with metastatic mucosal melanoma were included in the phase II trials with imatinib in KIT-mutated melanoma, but conjunctival melanomas are not separately mentioned." (PMID 32718045, 2020). "Moreover, when MNK1/2 were knocked down in KIT-mutant acral melanoma cells, their ability to translate SNAI1 and CCNE1 was compromised and their invasive and metastatic properties reduced." (PMID 32517051, 2020). "To conclude, CXCL8, THBS1 and KIT may be the hub genes in the metastasis of melanoma and thus may be regarded as therapeutic targets in the future." (PMID 32894090, 2020).